GDNF (glial cell derived neurotrophic factor)
Diseases named in the same sentence as GDNF in open-access papers (continued):
Sharing a sentence is not in itself a finding about the gene and the disease.
germ cell tumor (2 papers, 2012 to 2013). A benign or malignant, gonadal or extragonadal neoplasm that originates from germ cells. "GDNF is critical for self-renewal; overexpression of GDNF in mouse spermatogonial cells leads to the formation of germ cell tumors, whereas a GDNF knockout model results in an absence of germ cells." (PMID 23519268, 2013).
head and neck cancer (2 papers, 2020 to 2024). A primary or metastatic malignant neoplasm affecting the head and neck. "For example, nerve-derived glial cell line–derived neurotrophic factor (GDNF) activated JAK2-STAT1 signaling to further enhance PD-L1 expression in head and neck cancer." (PMID 38324026, 2024).
head and neck squamous cell carcinoma (2 papers, 2020). A squamous cell carcinoma that arises from any of the following anatomic sites: lip and oral cavity, nasal cavity, paranasal sinuses, pharynx, larynx, and salivary glands. "Nerve-derived GDNF increases programmed death ligand 1 (PD-L1) levels in head and neck squamous cell carcinoma cells by activating the JAK2-STAT1 signaling pathway, which in turn promotes the evasion of cancer cells from immune system surveillance in the nerve-cancer microenvironment." (PMID 32102656, 2020). "This study investigated the effect of GDNF on cell migration, growth, and response to radiation in preclinical models of head and neck squamous cell carcinoma (HNSCC) and correlated GDNF expression to treatment outcomes in HNSCC patients." (PMID 32084217, 2020).
Hepatic steatosis (2 papers, 2020 to 2022). Steatosis is a term used to denote lipid accumulation within hepatocytes. "In line with reduced hepatic steatosis, GDNF transgenic mice resist the development of hepatic inflammation when challenged with HFD." (PMID 32175323, 2020). "Overall, these findings have revealed that GDNF plays a crucial role in HFD-induced hepatic steatosis through its effect on autophagy and critical transcription factors such as PPARα, PPARγ, and Srebf1." (PMID 32175323, 2020). "GDNF transgenic mice are also protected from developing hepatic steatosis as manifested by decreased steatosis and substantially lower triglyceride accumulation in the liver as compared to controls." (PMID 32175323, 2020). "The protective role of transgenic expression of GDNF against hepatic steatosis was recapitulated in a more therapeutic approach by using GDNF-loaded nanoparticles." (PMID 32175323, 2020). "Increased expression of neurotrophic factors including GDNF, CNTF, BDNF, and NRG4 all alleviate hepatic steatosis." (PMID 32175323, 2020).
hepatocellular carcinoma (2 papers, 2016 to 2025). A malignant tumor that arises from hepatocytes. "Mutations in genes such as CHRDL2, STC1, CTGF, GDNF, and FGF7; which are involved in liver fibrosis and inflammation were highlighted, shedding light on their potential role in advancing MASLD towards more severe stages, including liver cirrhosis and hepatocellular carcinoma (HCC)." (PMID 39927143, 2025). "Cancer cells in the liver hepatocellular carcinoma (HCC), a non-nervous related cancer, highly overexpressed GDNF as compared to normal liver cells." (PMID 27167204, 2016).
Hypertension (2 papers, 2013 to 2017). The presence of chronic increased pressure in the systemic arterial system. "This led them to propose that these changes may predispose nephron deficient GDNF mice to glomerulosclerosis, glomerular injury and hypertension." (PMID 24019901, 2013).
infectious colitis (2 papers, 2011 to 2013). A viral or bacterial infectious process affecting the large intestine. "GFAP and GDNF as signs of activated EGCs are increased in the inflamed mucosa of patients with UC and infectious colitis, which underline an unspecific role of EGC in the regulation of intestinal inflammation." (PMID 21235736, 2011). "The highest increase of GDNF content could be observed in the inflamed colon of patients suffering from UC (812 ± 138 pg/ml, p < 0.05), and in patients suffering from infectious colitis (775 ± 93 pg/ml, p > 0.05)." (PMID 21235736, 2011). "The biopsies of patients with infectious colitis (Clostridium difficile) was characterized by a impressive increase of GFAP- and GDNF-positive structures similar to the inflamed gut biopsies of patients with UC." (PMID 21235736, 2011). "Here we determined the distribution of GFAP-positive EGCs and GDNF in the inflamed and non-inflamed colon of patients with CD, UC and infectious colitis." (PMID 21235736, 2011). "Although GDNF - anti-apoptic agent for epithelial cells- and GFAP is increased in the inflamed gut of CD, it is significantly less than in the inflamed intestines of UC patients or patients with infectious colitis." (PMID 21235736, 2011). "As the same is observed in the colon biopsies of patients suffering from infectious colitis, increased EGCs secreting GDNF might be not a specific phenomenon in IBD, but a general reaction of the mucosal ENS during gut inflammation." (PMID 21235736, 2011). "Therefore we investigated the GFAP content as marker for EGCs in the inflamed and non-inflamed intestines of patients with CD and UC in comparison to controls and patients with infectious colitis and postulate a diminished EGC network with reduced GDNF content in the intestines of patients with CD." (PMID 21235736, 2011).
insomnia (2 papers, 2024). A sleep disorder characterized by difficulty in falling asleep and/or remaining asleep. "The neurobiological underpinnings of both OSA and insomnia involve complex interactions among various neuromodulators, including brain-derived neurotrophic factor (BDNF), its precursor proBDNF, glial-cell-line-derived neurotrophic factor (GDNF), neurotrophin-3 (NTF3), and neurotrophin-4 (NTF4)." (PMID 39126038, 2024).
liposarcoma (2 papers, 2015 to 2018). A usually painless malignant tumor that arises from adipose tissue. "To investigate the relevance of our observations for human disease, we stained tissue samples from liposarcoma patients with GDNF, RETph, or MAZ antibody and determined the immune reactive scores." (PMID 25749382, 2015). "In summary, our data demonstrate that SPIN1 controls proliferation and survival of liposarcoma by regulating GDNF expression and thereby RET activation." (PMID 25749382, 2015). "Our data provide evidence that SPIN1 controls liposarcoma cell proliferation and apoptosis by directly enhancing the expression of GDNF, an activator of the RET signaling pathway." (PMID 25749382, 2015). "Thus, SPIN1 knockdown reduces liposarcoma cell-derived tumor growth in mice, which correlates with reduced levels of both GDNF mRNA and RET phosphorylation." (PMID 25749382, 2015). "Our mechanistic studies in vitro and in xenograft mouse models demonstrate that SPIN1, in cooperation with the transcription factor MAZ, controls proliferation and apoptosis of liposarcoma cells by directly regulating expression of the RET signaling pathway effector GDNF." (PMID 25749382, 2015). "Analysis of 155 patient samples revealed that levels of GDNF, activated RET (RETph), and MAZ were elevated in all four types of liposarcoma." (PMID 25749382, 2015). "Accordingly, knockdown of SPIN1 or MAZ results in reduced levels of GDNF and activated RET explaining diminished liposarcoma cell proliferation and survival." (PMID 25749382, 2015). "Together, these data suggest that MAZ and SPIN1 cooperate to regulate GDNF expression in T778 cells and that MAZ, at least in part, contributes to SPIN1-mediated control of liposarcoma cell proliferation and apoptosis." (PMID 25749382, 2015). "In accordance with these results, we observe increased levels of GDNF, activated RET, and MAZ in human liposarcoma compared to normal adipose tissue or lipoma." (PMID 25749382, 2015).
liver cancer (2 papers, 2016 to 2021). An epithelial or non-epithelial malignant neoplasm that arises from the liver. "Additionally, GDNF, was strongly overexpressed in human liver cancer cells, indicating solely blocking VEGF in these cancers would not be effective in preventing cancer progression and metastasis." (PMID 27167204, 2016). "GDNF can significantly activate hepatic stellate fibroblasts and promote liver fibrosis, participate in the microenvironment of liver cancer, affect the metabolism of extracellular matrix, and is closely related to the occurrence and progression of primary liver cancer." (PMID 34901153, 2021).
male infertility (2 papers, 2018 to 2021). The inability of the male to effect fertilization of an ovum after a specified period of unprotected intercourse. "Delineating the contribution of the CaN–NFAT pathway in regulating GDNF production in TECs presents therapeutic targets for male infertility." (PMID 30348976, 2018). "The present work, pertinent to male infertility in pre-pubertal candidates for gonado-toxic therapies, suggests that EPA acts as a modulator of SCs GDNF, promoting its epigenetic regulation and restoring SCs function damaged following radio or chemotherapy drugs." (PMID 34093450, 2021).
medullary sponge kidney (2 papers, 2018 to 2019). Medullary sponge kidney (MSK) is a birth defect of the tubules - tiny tubes inside the kidneys. "We saw a phenomenon of spontaneous biomineralization occurring in primary renal cells from a patient with medullary sponge kidney (MSK)—a clinical condition associated to nephrolithiasis and medullary nephrocalcinosis—who had a GDNF gene mutation." (PMID 31197147, 2019). "We had the chance to observe spontaneous instances of this phenomenon in primary renal cells derived from a patient with medullary sponge kidney (MSK) and interstitial nephrocalcinosis who carried a GDNF gene mutation." (PMID 29208768, 2018).
medullary thyroid cancer (2 papers, 2016 to 2021). "Here, we investigated RET activation and its biochemically interaction with CDK5 in GDNF-induced medullary thyroid cancer proliferation." (PMID 34207842, 2021). "In conclusion, our study reveals that CDK5 plays an essential role in regulating GDNF-induced human medullary thyroid cancer cell proliferation." (PMID 34207842, 2021). "Since CDK5 has been reported to play an essential role in various types of cancer cells, including medullary thyroid cancer cells, this study aimed to investigate the role of RET-mediated CDK5 activation and their interaction in GDNF-induced human medullary thyroid cancer proliferation." (PMID 34207842, 2021). "Interestingly, we identified for the first time that CDK5 physically interacts with RET protein in GDNF-induced medullary thyroid cancer cell proliferation." (PMID 34207842, 2021). "Overall, our data reveal that CDK5 activation occurs after RET activation by GDNF stimulation, suggesting that CDK5 may be a potential downstream of RET protein in GDNF-induced human medullary thyroid cancer cell proliferation." (PMID 34207842, 2021). "STAT3 activation status showed similar activation status with CDK5, suggesting that STAT3 activation might be CDK5-dependent in GDNF-induced medullary thyroid cancer cell proliferation." (PMID 34207842, 2021). "However, the role of CDK5 in GDNF-induced RET signaling in medullary thyroid cancer proliferation remains unknown." (PMID 34207842, 2021). "Since our current data also showed that GDNF enhanced p35/CDK5 activity in TT cell, therefore, we investigated similar signaling pathways that might be related to CDK5 activation in medullary thyroid cancer cell proliferation." (PMID 34207842, 2021). "Since we have previously reported that CDK5 phosphorylates STAT3 at Ser727 site in prostate and medullary thyroid cancer cells, thus, we thought that STAT3 might be a potential downstream of CDK5 in GDNF-induced RET signaling in medullary thyroid cancer cell proliferation." (PMID 34207842, 2021).
megacolon (2 papers, 2020 to 2021). "The potential of GDNF in regenerative medicine for HSCR was further demonstrated in that the postnatal administration of GDNF ameliorated megacolon symptoms and significantly prolonged the mean survival times of three out of four genetically distinct mouse models of HSCR." (PMID 34575824, 2021).
men2 (2 papers, 2013 to 2021). "Mammalian Ret is activated by GDNF to instruct epithelial morphogenesis in the uteric duct of the kidney and Ret-activating mutations have been implicated in a variety of human cancers including epithelial cancers (breast and lung) and multiple endocrine neoplasia (men2)." (PMID 23935447, 2013).
mental disorder (2 papers, 2017 to 2025). A disease that has its basis in the disruption of mental process. "Our results support a role for the GDNF signaling pathway and its interaction with stress in the development of abnormal behaviors relevant to SZ and other mental disorders." (PMID 29066960, 2017).
Motor neuron atrophy (2 papers, 2013 to 2022). Wasting involving the motor neuron. "GDNF is up to 2,500 times more potent than other neurotrophins, preserving approximately 100% of axotomized motor neurons and the only factor capable of reversing axotomy-induced motor neuron atrophy." (PMID 35360515, 2022).
nephrocalcinosis (2 papers, 2018 to 2019). Nephrocalcinosis is a disorder that occurs when too much calcium is deposited in the kidneys. "We thus confirmed the role of GDNF as an adaptive survival factor, and its alteration appears to have a key role in nephrocalcinosis." (PMID 29208768, 2018). "In conclusion, GDNF was confirmed as an adaptive survival factor, and its alteration appears to have a key role in nephrocalcinosis." (PMID 29208768, 2018). "The present study sought to ascertain whether down-regulating GDNF could lead to cell death and thus trigger a process of nephrocalcinosis under certain conditions." (PMID 29208768, 2018). "Having ascertained that GDNF massively favored the Ca2PO4 deposition process in our in vitro model of nephrocalcinosis, we investigated whether cell death had occurred under the same conditions." (PMID 29208768, 2018).
obsessive-compulsive disorder (2 papers, 2018 to 2021). A disorder characterized by the presence of persistent and recurrent irrational thoughts (obsessions), resulting in marked anxiety and repetitive excessive behaviors (compulsions) as a way to try to decrease that anxiety. "Interestingly, escitalopram increased the serum levels of both GDNF and BDNF in obsessive-compulsive disorder in rats." (PMID 33802323, 2021).
pancreatic adenocarcinoma (2 papers, 2018 to 2020). "In human pancreatic adenocarcinoma, soluble GFRα1 was shown to be released from nerves and interacted with soluble GDNF to enhance perineural invasion, an event that is also observed in HNSCC." (PMID 32084217, 2020). "In human pancreatic adenocarcinoma tissues and MiaPaCa-2 cell lines, binding of GDNF to its receptor GFRα1 stimulates PNI via GDNF-(Ret proto-oncogene) RET signaling pathway." (PMID 29334991, 2018).
pneumococcal meningitis (2 papers, 2017 to 2022). An acute purulent infection of the meninges and subarachnoid space caused by Streptococcus pneumoniae, most prevalent in children and adults over the age of 60. "In our experiment, we observed that lithium prevented memory impairment and increased hippocampal BDNF, NGF, and GDNF neurotrophin expression in experimental pneumococcal meningitis." (PMID 29200666, 2017). "The aim of this study was to investigate the effects of lithium on brain-derived neurotrophic factor (BDNF), nerve growth factor (NGF), and glial cell line-derived neurotrophic factor (GDNF) expression in the hippocampus and on memory in experimental pneumococcal meningitis." (PMID 29200666, 2017). "Among those drugs, we studied the effect of tamoxifen as well as lithium on BDNF, GDNF, and NGF expression in the hippocampus and on behavior tasks in an experimental model of pneumococcal meningitis in rats." (PMID 29200666, 2017). "Hence, the aim of this study was to investigate the effects of lithium and tamoxifen on BDNF, GDNF, and NGF expression in the hippocampus and on behavior tasks in an experimental model of pneumococcal meningitis." (PMID 29200666, 2017).
prostate tumor (2 papers, 2015 to 2016). "Analogously, GDNF has recently been reported to function in a paracrine manner to promote a prostate tumor cell resistant phenotype in response to ionizing radiation and cytotoxic agents." (PMID 26675549, 2016). "In the prostate itself, GDNF-induced chemotaxis of prostate tumor cells could induce cell migration to areas of sustained viability and niches with more favorable growth conditions after genotoxic insults." (PMID 25575823, 2015).
Sertoli Cell-Only Syndrome (2 papers, 2013 to 2021). A type of male infertility in which no germ cells are visible in any of the biopsied SEMINIFEROUS TUBULES (type I) or in which germ cells are present in a minority of tubules (type II). "Consistent with our observations in mice, GDNF was similarly downregulated in human testes with Sertoli cell-only syndrome." (PMID 34143973, 2021). "GDNF has been shown to be essential for fate determination of SSCs, since in aging males heterozygotes for GDNF deletion, testes appear devoided of germ cells and show a phenotype similar to Sertoli-cell-only syndrome." (PMID 24324457, 2013).